GALR1 (galanin receptor 1)
Diseases named in the same sentence as GALR1 in open-access papers (continued):
Sharing a sentence is not in itself a finding about the gene and the disease.
salivary duct carcinoma (2 papers, 2019 to 2022). An aggressive, high grade adenocarcinoma that arises from the salivary glands. "Recently, it was reported that aberrant GALR1 promoter methylation is significantly associated with shortened survival in salivary duct carcinoma patients." (PMID 30901947, 2019).
squamous cell carcinoma (2 papers, 2019 to 2022). A carcinoma arising from squamous epithelial cells. "Moreover, in samples from clinical squamous cell cancer, six genes (GAL, GSTP1, MRPL11, MRPL21, SF3B2, and YIF1A) at 11q13.1–13.3 and one gene (GALR1) at 18q23 showed significant differences in expression between normal and tumor samples." (PMID 31552180, 2019).
acute endometritis (1 paper, 2021). An acute, usually bacterial infection affecting the endometrium. "Eight days later, the E. coli group developed severe acute endometritis and lowered GALR1 protein expression in the myometrium." (PMID 34203944, 2021).
acute myocardial infarction (1 paper, 2019). Necrosis of the myocardium, as a result of interruption of the blood supply to the area. "In accord with this study, GalR1 inhibitor, M40 improves cardiac function and attenuate remodeling after myocardial infarction in rats." (PMID 32039239, 2019).
deafness (1 paper, 2020). An inherited or acquired condition characterized by the complete loss of the ability to hear from one or both ears. "A large mutation screening of 307 deafness genes in patients with microtia identified GALR1 as a strong candidate gene (amongst others) with novel mutations associated with microtia." (PMID 33192958, 2020).
demyelination (1 paper, 2012). "In contrast with GalR1 expression, the expression of GalR2 was increased 1.4- and 2.1-fold in WT and Tg mice, respectively, in the demyelination groups; expression of GalR2 increased 2.2- and 3.3-fold in WT and Tg mice, respectively, in the recovery groups." (PMID 22442732, 2012).
developmental delays (1 paper, 2022). "The region related to developmental delays and abnormal cerebral white matter development is 18q22.3q23, and the possible related pathogenic genes are ZNF236, ZNF516, MBP, GALR1 and lOC284276." (PMID 36123715, 2022).
dyslipidemia (1 paper, 2023). "Manipulation of L. reuteri–capric acid–GALR1 axis paves way for clinical therapeutic strategies to prevent biorhythm disorder-ignited dyslipidemia in PCOS women." (PMID 37422471, 2023). "On the other hand, GALRs antagonist M40 was used to verify the role of galanin-GALR1 in darkness-induced dyslipidemia." (PMID 37422471, 2023). "Our results also illustrated GALR1 antagonist (M40) as a potential therapeutic target for dyslipidemia in circadian disruption-ignited PCOS." (PMID 37422471, 2023). "GALR1 agonist M617 was used to certify the vital role of GALR1 in the alleviation of L. reuteri on dyslipidemia." (PMID 37422471, 2023). "This study highlights the importance of L. reuteri–capric acid–GALR1 axis in the maintenance of lipid homeostasis, which may serve as an efficacious target in the treatment of biorhythm disorder-ignited dyslipidemia in PCOS." (PMID 37422471, 2023). "Accordingly, we suggest that the catabolism of capric acid might be enhanced by L. reuteri and the activated GALR1 signaling due to capric acid was thus restrained in DL.reuteri rats, contributing to the amelioration of dyslipidemia." (PMID 37422471, 2023). "Therefore, GALR1 might mediate the ability of galanin to regulate dyslipidemia." (PMID 37422471, 2023).
ear malformation (1 paper, 2020). "Interestingly, a case report of a patient with congenital aural atresia (typically resulting in unilateral or bilateral ear malformation) caused by chromosome 18q deletion, also contained the GALR1 gene." (PMID 33192958, 2020).
endometritis (1 paper, 2021). An acute or chronic, usually bacterial infectious process affecting the endometrium. "The current report presents the action of endometritis on the GALR1 and GALR2 protein expression in the myometrium, and the importance of GAL, GALR1, and GALR2 in the contractile activity of a pig uterus with inflammation." (PMID 34203944, 2021).
Hepatic steatosis (1 paper, 2023). Steatosis is a term used to denote lipid accumulation within hepatocytes. "Spexin, a neuropeptide in the galanin family, has been shown to activate GALR2/GALR3 (but not GALR1) and mitigate diet-induced hepatic steatosis in vivo and in vitro by activating GALR2." (PMID 37180164, 2023).
Hyperglycemia (1 paper, 2017). An increased concentration of glucose in the blood. "Furthermore, administration of a centrally active galanin analog with high affinity for GalR1 has been recently shown to reduce insulin secretion and promote hyperglycemia, providing a further understanding on the role of GalR1 in vivo." (PMID 28729853, 2017).
Hypertension (1 paper, 2006). The presence of chronic increased pressure in the systemic arterial system. "Conversely, some of the additional genes in the hand complied list, such as GALR1, are not linked in any way to hypertension in PubMed, even with a more sophisticated profile based search, and including all abstracts." (PMID 16551372, 2006).
injury (1 paper, 2012). Damage inflicted on the body as the direct or indirect result of an external force, with or without disruption of structural continuity. "In conclusion, Gal, via acivition of GalR1 and/or GalR2, may have neuoprotective effects in reducing neuropathic pain behaviors and improving nerve regeneration after nerve injury." (PMID 22624057, 2012).
laryngeal carcinoma (1 paper, 2015). Carcinoma that arises from the laryngeal epithelium. "However, in laryngeal carcinoma cell lines, an anti-GALR1 antibody induced ERK activation, suggesting that GALR1 is a negative regulator of ERK." (PMID 26251921, 2015).
liver cancer (1 paper, 2023). An epithelial or non-epithelial malignant neoplasm that arises from the liver. "On the contrary, because the GALR1 marker suffered from low levels of methylation in TCGA liver cancer tissue (median beta value 0.09), the specificity of 94% corresponds to a sensitivity of only 46%, making it a poor marker for detection of this cancer type." (PMID 37835520, 2023). "Importantly, ZNF154 enabled near-perfect classification of liver cancer samples with an AUC of 0.92, whereas GALR1 and TLX1 only produced AUC values of 0.64 and 0.77, respectively." (PMID 37835520, 2023).
lung adenocarcinoma (1 paper, 2023). A carcinoma that arises from the lung and is characterized by the presence of malignant glandular epithelial cells. "Additionally, GALR1 showed significant differential methylation in lung adenocarcinoma samples, despite the low number of tumor samples (n = 3)." (PMID 37835520, 2023). "However, the utility of this marker cannot be ruled out, since the compromise in specificity led to GALR1, reaching the highest sensitivity as a multi-cancer assay within kidney, pancreatic, and lung adenocarcinoma." (PMID 37835520, 2023).
lung carcinoma (1 paper, 2013). "Of the 42 common Significant hypermethylated genes unique to Stages I and III, GALR1, NID2 have been identified as highly methylated in NSCLC, PAX7 has been identified in lung cancer but not reported with methylation, though PAX family genes have been previously reported being methylated in cancer." (PMID 24369052, 2013).
neuropathy (1 paper, 2017). A disorder affecting the nervous system that manifests with pain, tingling, numbness, and/or muscle weakness. "Our results have demonstrated that GalR1 is involved in the galanin-induced antinociception in the CeA in normal rats and rats with neuropathy." (PMID 29127424, 2017). "There is a significant increase in the content of GalR1 (t = 6.24, P < 0.01) in CeA in rats with neuropathy than that in normal rats tested by western blot." (PMID 29127424, 2017). "There is an increased trend in the mRNA level of GalR1 (t = 1.04, P = 0.30) in CeA in rats with neuropathy than that in normal rats tested by RT-PCR." (PMID 29127424, 2017). "Taken together, the results of present study illustrate that galanin plays an important role in nociceptive modulation in CeA in rats with neuropathy, and there may be an up-expression of GalR 1 in CeA during neuropathic pain." (PMID 29127424, 2017). "Moreover, there was a significant increase in GalR1 content in CeA in rats with neuropathy than that in normal rats." (PMID 29127424, 2017). "The present study was performed to explore the role of galanin and galanin receptor 1 (GalR 1) in nociceptive modulation in the central nucleus of amygdala (CeA) in normal rats and rats with neuropathy, and the involvement of GalR 1 and PKC was also investigated." (PMID 29127424, 2017). "It was found that to inhibit the galanin-induced antinociception should use high dose of M40 (1 nmol) than that in normal rats (0.5 nmol) (unpublished data), supporting the results that GalR1 content in CeA significantly increased in rats with neuropathy than that of normal rats." (PMID 29127424, 2017). "Furthermore, we found that both galanin mRNA expression and galanin content showed no significant changes in CeA in rats with neuropathy than that in normal rats, while GalR 1 content increased significantly in CeA in rats with neuropathy than that in normal rats." (PMID 29127424, 2017).
nicotine dependence (1 paper, 2023). Physical and psychological dependence on nicotine. "The GALR1 SNP rs9959924 we identified to be potentially associated with verbal retention was previously studied in relation to smoking and nicotine dependence and found to be significantly associated with smoking quantity." (PMID 38254919, 2023).
oral squamous cell carcinoma (1 paper, 2015). "GALR1, galanin receptor subtype 2, suppresses cell proliferation in several cancers such as head and neck and oral squamous cell carcinoma." (PMID 25657825, 2015).
prostate carcinoma (1 paper, 2023). A carcinoma that arises from epithelial cells of the prostate gland. "S1PR3 expression level was higher in AA than EA prostate cancer patients whereas GALR1, CHRM3, and NPFFR1 expression level was lower in AA than EA prostate cancer patients." (PMID 36937425, 2023).
sarcoma (1 paper, 2019). A usually aggressive malignant neoplasm of the soft tissue or bone. "Its human syntenic region, Hs-18q23, is recurrently deleted in sarcomas and contains two genes, GALR1 and CYB5A, that are annotated as tumor suppressors." (PMID 30947707, 2019).
Seizure (1 paper, 2010). A seizure is an intermittent abnormality of nervous system physiology characterized by a transient occurrence of signs and/or symptoms due to abnormal excessive or synchronous neuronal activity in the brain. "Enhanced susceptibility to excitotoxin-induced neuronal injury in GalR1 knock-out mice has been observed and galanin overexpression is known to decrease hippocampal neuronal injury resulting from limbic seizures, presumably via GalR1 receptor modulation." (PMID 21179451, 2010).
temporal lobe epilepsy (1 paper, 2020). A localization-related (focal) form of epilepsy characterized by recurrent seizures that arise from foci within the temporal lobe, most commonly from its mesial aspect. "Finally, GALR1 has been linked to temporal lobe epilepsy (TLE) and galanin agonists inhibit seizures." (PMID 33218114, 2020).
Tinnitus (1 paper, 2020). Tinnitus is an auditory perception that can be described as the experience of sound, in the ear or in the head, in the absence of external acoustic stimulation. "Notably, we identified KCNN3, SOD3, MUC4, GALR1, and WDR45B, which are implicated in auditory function, as differentially methylated associated with self-reported tinnitus." (PMID 33192958, 2020). "Notably, tinnitus symptom analyses identified regions with differential methylation in genes KCNN3, MUC4, GALR1, SOD3, and WDR45B (in the low vs. high cumulative blast exposed groups." (PMID 33192958, 2020).
type 2 diabetes mellitus (1 paper, 2016). A type of diabetes mellitus that is characterized by insulin resistance or desensitization and increased blood glucose levels. "This study contributes to our understanding of the central role of GalR1 in benefit of glucose uptake and insulin sensitivity, offering a possibility that the GalR1 may be taken as a potential therapeutic target for type 2 diabetes mellitus." (PMID 27127795, 2016). "Therefore, in this study the effects of i.c.v. injection of a GalR1 agonist, M617 on insulin sensitivity, and insulin signaling in the adipose tissue of type 2 diabetic rats were evaluated." (PMID 27127795, 2016).
ulcerations (1 paper, 2016). "The relationship between galanin and GalR1 upregulation, and the function of the pyloric sphincter should be further studied in terms of gastric emptying problems in patients with antral ulcerations." (PMID 27175780, 2016).
uterine cancer (1 paper, 2023). Primary or metastatic malignant neoplasm involving the uterine corpus and/or the cervix. "GALR1 also met the 0.40 threshold in nine tumor types: bladder, breast, colon, head and neck, lung, prostate, rectal, stomach, and uterine cancer." (PMID 37835520, 2023).
Vestibular schwannoma (1 paper, 2021). A vestibular schwannoma (also known as acoustic neuroma, acoustic neurinoma, or acoustic neurilemoma) is a benign, usually slow-growing tumor that develops from the VIIIth cranial nerve supplying the inner ear. "PRICKLE1 mRNA is significantly down-regulated in vestibular schwannomas, while GALR1 is abundant in neuroactive ligand-receptor interactions, and both PRICKLE1 and GALR1 are targets of hsa-miR-30c-5p and hsa-miR-30a-5p, suggesting that hsa-miR-30 may play a key role in vestibular schwannomas." (PMID 33673851, 2021).
tumor (27 papers, 2002 to 2023). "Loss of GALR1 expression is associated with its promoter hypermethylation supporting the hypothesis that GALR1 acts as a tumor suppressor gene." (PMID 26504828, 2015). "Considering each of the markers individually, ZNF154 reached 82% sensitivity, while TLX1 and GALR1 correctly classified 90% and 95% of the tumor samples, respectively." (PMID 37835520, 2023). "While GALR1 showed superiority in classifying TCGA tumor versus normal tissue derived from breast, kidney (KIRC) and lung (LUAD), it suffered from increased methylation levels in normal blood cells." (PMID 37835520, 2023). "Lastly, GALR1 has also been documented to multiple correlations with tumour stages, lymph node status and the expression levels of SLITRK3 and SIGIRR genes." (PMID 36329447, 2022). "These investigations revealed that the GALR1 promoter was widely hypermethylated in HNSCC cell lines and primary tumor specimens, and its methylation was closely related to reduce expression of GALR1." (PMID 33150179, 2020). "Many studies have demonstrated that GALR1 plays a tumor suppressor role in different types of cancers." (PMID 33150179, 2020). "Ectopic expression of GALR1 suppresses tumor cell proliferation through Erk1/2-mediated regulation of cyclin-dependent kinase inhibitors and cyclin D1." (PMID 31105737, 2019). "Recent studies have provided strong evidence supporting the tumor suppressive effects of galanin, GALR1, and GALR2, and they suggested that the inhibition of cell proliferation and apoptosis by galanin occurred via its receptors." (PMID 29462183, 2018). "There was only one tumor suppressor (CSF2) and one cancer census gene in Cluster 3 (USP6); there are four tumor suppressors (GALR1, IRF4, PTPRT and SOX11) and one more cancer census gene in Cluster 4 (NRG1)." (PMID 28198667, 2017). "Our preliminary analyses have indicated that methylation-induced GALR1 gene silencing is a critical event in HNSCC progression associated with LOH of 18q, and that activation of GALR1 signaling suppresses tumor cell proliferation." (PMID 28616099, 2017). "Methylation of GALR1 was significantly correlated with tumor size (P = 0.002) and clinical stage (P = 0.009)." (PMID 27027429, 2016). "Whereas the mRNAs of genes that helps in tumor inhibition like Galr1, tumor suppressor Gnmt and Fn3k were significantly increased." (PMID 26429877, 2015). "The experiments using clinical HNSCC samples demonstrated that GALR1 methylation was significantly correlated with reduced survival rates, tumor stage, lymph node status, increased tumor size, cyclin D1 expression and p16 methylation." (PMID 26251921, 2015). "In multivariate analysis, taking into account age, tumor site, smoking, tumor stage, and cyclin D1 expression, only GALR1 methylation and stage were significant predictors of poor survival." (PMID 26251921, 2015). "Interestingly, the combination of ZNF154 with either TLX1 or GALR1 resulted in the successful detection of all tumor samples (100% sensitivity)." (PMID 37835520, 2023). "A second methylation probe, cg03502002 in GALR1 (hg19/chr18:74,962,134), showed an average difference in median beta value between tumor and normal of 0.43, with the smallest difference detected in KIRP (0.02) and the largest difference again found in UCEC (0.70)." (PMID 37835520, 2023). "Thus, ZNF154, TLX1, and GALR1 methylation were elevated across the majority of tumor-derived cell lines." (PMID 37835520, 2023). "Moreover, the elevated immunoexpression of GALR1 in submucosal plexuses close to cancer correlated with the status of the primary tumour (T), presence of distant metastasis and TNM stage." (PMID 36551197, 2022). "The GALR1 gene is a candidate gene that is mapped to chromosome 18q23, suggesting that alterations in this receptor may promote tumor progression and poor survival." (PMID 34885121, 2021).